BCL6 (BCL6 transcription repressor)
Diseases named in the same sentence as BCL6 in open-access papers (continued):
Sharing a sentence is not in itself a finding about the gene and the disease.
tumor (continued). "BCL6+ cells could be found in every tumor section examined, from 0.96–45% positive tumor cells, with an average of 10% of cells within a tumor expressing BCL6 protein." (PMID 32320427, 2020). "However, KO mice derived Treg cells exhibited remarkably reduced expression of Foxp3 and CTLA4 in both tumor tissue and dLNs, suggesting a compromised stability and function of Bcl6-dificient Treg cells." (PMID 32477338, 2020). "Although Bcl6 deletion alone greatly improved the therapeutic efficacy, the combination of Bcl6 deletion and anti-CTLA4 or anti-PD1 did exhibit additional effects at delaying tumor growth, indicating that Bcl6 can be a potential therapeutic target combined with ICB in cancer immunotherapy." (PMID 32477338, 2020). "Thus, it is well possible that the effects of continuous and effective inhibition of BCL6 exceed the tumor stasis observed in our model." (PMID 32180900, 2020). "Different studies suggested a proto-oncogene role for BCL6 and a tumor suppressor role for ZBTB28." (PMID 32517789, 2020). "Xenograft model suggested that BCL6 induces tumor growth and suppresses apoptosis." (PMID 31903146, 2020). "In mice that received wild-type OT-1 T cells, around 3% of tumor-infiltrating CD8 T cells were transferred cells, whereas Bcl6-deficient OT-1 T cells could reconstitute around 1% of tumor infiltrating CD8 T cells." (PMID 32845913, 2020). "A tumor-suppressor role for FBXO11 was first discovered in DLBCL, where it is mutated in up to 10% of cases and selectively ubiquitinates the germinal-center transcription factor BCL6 leading to its degradation." (PMID 33024076, 2020). "These cells could serve as a source of tumor-infiltrating CD62L+Bcl6+ cells for a long period of time, even after the effector cells became exhausted." (PMID 32845913, 2020). "Importantly, we demonstrated that DNA damaging cancer therapies up-regulated BCL6 expression in vitro and in an intra-cranial tumor model in vivo, and that blockade of BCL6 enhanced the efficacy of those therapies." (PMID 32320427, 2020). "Bcl6+ cells were part of Tcf1+ cells in tumor-infiltrating CD8 T cells." (PMID 32845913, 2020). "Moreover, we demonstrated that targeting Bcl6 in Treg cells is sufficient to inhibit tumor growth and further improve the efficacy of ICB." (PMID 32477338, 2020). "NASH progression and NASH-derived tumours were suppressed in the Bcl6-LKO mice." (PMID 32546802, 2020). "Moreover, Bcl6 is essential in maintaining Treg cell lineage identity within tumor microenvironment." (PMID 32477338, 2020). "However, the role of BCL6 in tumor maintenance remains poorly investigated due to the absence of suitable genetic models and limitations of pharmacological inhibitors." (PMID 32180900, 2020). "Consequently, CD62LintCD44high T cells that appeared upon antigen priming in tumor-draining lymph nodes maintained their potential for expansion by expressing Bcl6 after tumor infiltration." (PMID 32845913, 2020). "In many sections the BCL6+ cells appeared to be perivascular, so the variation in the number of BCL6+ tumour cells between samples may represent a coincidental difference in the vascularity of sections sampled." (PMID 32320427, 2020). "Based on our data, we presented a hypothetical model that ZBTB16 might form complexes with ZBTB28 and BCL6, respectively, and function as a tumor suppressor through inhibition of BCL6 and promotion of ZBTB28." (PMID 32517789, 2020). "BCL6 protein expression was examined by immunohistochemistry in 62 GBM tumor specimens." (PMID 32320427, 2020). "Next, we sought to investigate the role of Bcl6 during tumor metastasis." (PMID 32477338, 2020). "Notably, Bcl6 is essential in maintaining the lineage stability of Treg cells in tumor microenvironment." (PMID 32477338, 2020).
tumor (continued). "Epigenetic modulation of the BACH2/BCL6 axis may therefore be an additional mechanism to regulate tumor cell apoptosis and proliferation." (PMID 30841886, 2019). "Interestingly, BCL6 is essential for the function of ZBTB28 as a tumor suppressor in cancer cells, however, BCL6 lost its cancer-promoting function when ZBTB28 expression was present." (PMID 31754389, 2019). "This miRNA has been shown to target the proto-oncogene BCL6 transcription repressor and therefore increased expression may suggest heightened tumour suppressor activity after chemotherapy." (PMID 31826004, 2019). "One patients with Bcl6+/MUM1- had 4 areas of involvement with the largest tumor diameter < 1.5 cm." (PMID 31189479, 2019). "In addition, BCL-6 gene also regulates tumor growth by regulating the expression of other genes, such as signal transducers and activators of transcription (STAT) and B lymphocyte induced maturation protein-1 (Blimp-1) and others." (PMID 30666200, 2018). "The DH-My6 cell line was generated from tumor tissue of a patient with MYC/BCL6 DHL." (PMID 30323893, 2018). "Thus, tumor cells often express pan B-cell markers (cluster of differentiation 19 [CD19], CD29, CD79a) and in 90% of cases express BCL-6 and MUM1, whereas plasma cell-associated proteins such as CD38 and CD138 are usually absent." (PMID 30446015, 2018). "miR-127 has been identified as a potent inhibitor of the anti-apoptotic protein Bcl6, and therefore may have tumor suppressive properties." (PMID 29988972, 2018). "According to previous reports, the staining could be judged as positive if the number of tumor cells positive for C-MYC ≥ 40%, BCL-2 ≥ 50%, or BCL-6 ≥ 30% of tumor tissues." (PMID 30666200, 2018). "Furthermore, it is essential to note that endothelial Bcl-6/BCoR were found to be induced by tumor-derived stimuli in our initial experiments." (PMID 27880939, 2017). "However, subsequent transcript analysis by quantitative real-time PCR demonstrated a rapid, 5- to 17-fold induction of both Bcl-6 and BCoR mRNA in ECs within 1 h of stimulation with tumor-derived signals." (PMID 27880939, 2017). "Furthermore, the impact of Bcl-6 inhibition on microvessel density and tumor growth was addressed, since soluble Bcl-6 inhibitors have been developed for clinical cancer therapy." (PMID 27880939, 2017). "Furthermore, chronic overexpression of BCL6 appears to sensitize tumor cells to chemotherapy exposure coincident with increased ALL cell proliferation and blunted tumor cell quiescence." (PMID 27015556, 2016). "This reduction in BCL6 abundance was most pronounced and consistently observed in leukemic cells recovered from the PD population, which we have previously characterized as a chemotherapy-resistant population representative of resistant tumor populations." (PMID 27015556, 2016). "Although not statistically significant mice injected with ALL cells overexpressing BCL6 had a lower median percentage (45.6% GFP+) of human tumor cells compared to those injected with vector control cells (54.1% GFP+) 24 hours after the conclusion of Ara-C treatment." (PMID 27015556, 2016).
tumor (continued). "Consistent with western blot observations, flow cytometry and confocal microscopy analysis of REH and Nalm-27 cell lines showed that leukemic cells recovered from the PD population of BMSC or HOB co-culture had reduced BCL6 protein abundance compared to tumor cells cultured in media alone." (PMID 27015556, 2016). "BL is composed of monomorphic B-cells with basophilic cytoplasm and numerous mitotic figures that express B-cell antigens such as IgM, CD19, CD20, CD22, and CD79b, germinal center markers such as CD10 and BCL-6, and the proliferation marker Ki-67 in nearly all tumor cells." (PMID 27818811, 2016). "The follicles that are colonized result in a nodular architecture with partial positivity for CD10 and BCL6 due to the pre-existent germinal center cells that are in the same compartment as the tumor cells and acquisition of BCL6 expression by the colonizing neoplastic cells." (PMID 26949422, 2016). "Furthermore, chronic forced expression of BCL6 in this quiescent tumor cell population resulted in sensitization to chemotherapy." (PMID 27015556, 2016). "Utilizing this co-culture model to represent BMM protected and resistant ALL cells we found that co-culture with BMSC or HOB reduced the abundance of tumor cell BCL6, coincident with increased survival and quiescence of a subset of tumor cells in contact with BMSC or HOB." (PMID 27015556, 2016). "Notably, miR-146a overexpression also led to the repression of certain mRNAs that are important in B-cell differentiation including Blimp1 and Bcl6, once again supporting the notion of miR-146a playing a role in the maturation stage of the tumor cells." (PMID 25906746, 2015). "Furthermore, direct cell-cell incubation induces an upregulation of mitotic genes Aurora B and Plk1, cytokine genes IL-6 and IL-8 and the oncogene BCL6 known for their tumor promoting functions." (PMID 26439686, 2015). "Moreover, forced expression of BCL6 increased tumor growth and invasiveness in a nude mouse xenograft model." (PMID 24917186, 2014). "BCL6 and CD79a were expressed in the tumor cells of both components in all cases." (PMID 24885870, 2014). "ZFP161 is not known to exert oncogenic activity within humans, and indeed its expression in some tumours is more consistent with a potential tumour suppressor role, however, Bcl6, one of the best-characterised mammalian oncogenic family members, offers striking parallels to the function of Ab." (PMID 23874226, 2013). "In particular, the null expression of CD10 and Bcl-6 excluded the follicular origin of this tumour." (PMID 23420489, 2013). "To test whether viability of entire tumor cell population is dependent on BCL6 and /or pSTAT6 functions within a subset of cells, we applied a cellular assay using recently developed specific inhibitors." (PMID 23852366, 2013). "Some of these aberrant SHMs may occur at proto-oncogenes, such as BCL6 and/or tumor suppressors i.e. BACH2, giving cells growth advantages and eventually leading to malignant transformation." (PMID 22808135, 2012). "Therefore, the tumor cells often express germinal center associated markers, such as CD10 and Bcl-6." (PMID 22726497, 2012). "These included transcription factor EGR1 which is reported to have tumor suppressor properties, genes involved in lymphocyte activation and differentiation such as BCL6, CD4 and SMAD3 and genes TLR3 and TIRAP that are part of the toll-like receptor signaling pathway." (PMID 23072359, 2012). "Alterations observed in the G1-S checkpoint of H/RS cell cycle, in the principal tumor suppressor pathways Rb-p16INK4a and p27KIP1, and the high rate of proliferation (MIB1, BCL6) are also strongly associated with higher infiltration of the overall immune response against the tumor." (PMID 22927872, 2012). "Loss of CDKN2B and gain of BCL6, FGF3, and PTP4A3 predicted tumor." (PMID 22570652, 2012).
tumor (continued). "Moreover, we analyzed the levels of mRNA and BCL2 and BCL6 protein in DLBCL tumor tissues by PCR and immunohistochemistry (IHC), respectively." (PMID 20016842, 2009). "Additionally, IL-35/STAT3/PAX5/BCL6 signaling-driven transcriptional dysregulation in naïve B cells could impair their differentiation into anti-tumor effector cells." (PMID 41522514, 2026). "However, unique alterations such as BCL6 in metastatic lesions may represent late events or adaptations important for tumor spread and therapy resistance." (PMID 41597409, 2026). "Interestingly, the expression of PLAAT4, a tumor suppressor associated with the PI3K-AKT pathway, was negatively correlated with the expression of BCL6." (PMID 40777995, 2025). "Importantly, the upregulation of Bcl-6 to T-bet at the late stage, coinciding with the time when the anti-viral response waned but anti-tumor responses persisted, allowed for the expansion of a memory CD4+ T-cell subset that was responsible for long-lasting protective anti-tumor immunity." (PMID 39885128, 2025). "Additionally, elevated AID/POLH-mediated mutagenesis and BCL6-IGH breakpoints in the IGH S region suggest that tumor cells may have undergone GC reactions." (PMID 40780199, 2025). "Notably, tumor cells isolated from the Bcl6 transgenic and the Myc/Bcl6 transgenic mice displayed reduced Dyrk1a mRNA expression levels, indicating that Dyrk1a may be negatively regulated either by Bcl6 or Myc in these models." (PMID 40148558, 2025). "Notably, BCL6 was observed to be overexpressed in exhausted T-cells and may play a role in tumor immune escape." (PMID 38248118, 2024). "Therefore, we can conclude that Bcl6 inhibited T cells mediated tumor rejection." (PMID 38956432, 2024). "Moreover, BCL6 inhibitors have shown potent effects against these tumor types." (PMID 38951817, 2024). "Univariate analysis showed that compared with the high expression group of BCL6, the low expression group of BCL6 exhibited advanced pN stage (P = 0.013), increased lymph node (LN) metastasis (9.89 ± 9.12 vs. 7.16 ± 11.83, P = 0.001), and long tumor diameter (6.81 ± 3.51 vs. 5.38 ± 2.22, P = 0.012)." (PMID 37060074, 2023). "Furthermore, low BCL6 expression in GC indicated larger tumor size, more LNs, and poor prognosis." (PMID 37060074, 2023). "BCL6 may have a specific role in tumor progression, depending on the tissue and organ involved." (PMID 37060074, 2023). "However, the tumor-specific regulatory network of BCL6 remains elusive." (PMID 36377663, 2022). "In addition, to investigate whether iRGD-Exo-BCL6 siRNA could affect the expressions of BCL6 and active caspase 3 in tumor tissues in vivo, a mouse OCI-Ly8 subcutaneous xenograft model was established." (PMID 35982974, 2022). "Our current work, along with the recently published studies, suggest a crucial role of BCL6 in rendering tumor cells more tolerant to treatments and a model in which multiple factors may contribute to BCL6 upregulation and BCL6-mediated signaling during this process." (PMID 35503721, 2022). "BCL6 was shown to participate in the regulation of Treg cellular immune responses in colorectal tumorigenesis and may be explored a therapeutic target of anti-tumor immunity." (PMID 35721059, 2022). "Additionally, our data indicate that Bcl6 is rapidly induced upon tumor stimulation, implying that there might exist pre-synthesized Bcl6 mRNA, facilitating its rapid elicitation upon stimulation and setting the basis for recall-like responses." (PMID 36542153, 2022). "Mechanistically, we showed that transcriptional factor Bcl6 co-opted the demethylase Tet2 and the deacetylase SIRT1 to confer the epigenetic imprinting and mitochondrial metabolic traits to SMMs, bolstering the stability and longevity of trained immunity in tumor-associated macrophages (TAMs)." (PMID 36542153, 2022).
tumor (continued). "Moreover, we speculate that BCL6 may functionally program tumor pro-survival signals in drug response and can be used as a predictive biomarker for therapy resistance." (PMID 35503721, 2022). "Specifically, we identify a Bcl6+CD11b+F4/80+Ly6C− macrophage subpopulation, which are featured with expression of stem-related genes, self-renewing potential, and importantly, long-term maintenance of pro-tumor activity, and therefore termed stem-like memory macrophages (SMMs)." (PMID 36542153, 2022). "Sample F16 could now be classified as “double-hit” (DH) for MYC and BCL2 rearrangements, sample F67 as a MYC and BCL6 DH tumor (with partners IGH and IGL), sample F194 as MYC and BCL2 and BCL6 triple hit (TH, although MYC and BCL6 fused together) and sample F209 as TH." (PMID 34099699, 2021). "However, the BCL-6 corepressor (BCOR) enhances the inhibition of BCL-6 in tumour cells." (PMID 34961030, 2021). "Both miR-10a and miR-187 act as tumor suppressors by regulating BCL6 expression through induction of cell apoptosis as shown in cell culture and tumor microarray studies suggesting these miRNAs could be exploited as a novel therapeutic target for DLBCL treatment." (PMID 34679437, 2021). "In this study, to specifically assess the role of Bcl6 in tumor infiltrating Treg cells, we challenged Bcl6fl/flFoxp3Cre mice with tumor cells and found that tumor growth was retarded in Bcl6fl/flFoxp3Cre mice with decreased tumor weight at the end point when compared to WT counterparts." (PMID 32477338, 2020). "Thus, promotion of continuous proliferation and self-renewal of CD62LintCD44high cells in secondary lymphoid tissues could help supply CD62L+Bcl6+ cells within the tumor, augmenting anti-tumor immunity." (PMID 32845913, 2020). "In G1/G2 tumor samples, BCL6 mutation did not change as compared to the control." (PMID 29854311, 2018). "The observation that the Bcl-6 inhibitor 79-6 enhanced endothelial sprouting in vitro and in vivo led to the pertinent question whether the anti-cancer compound might exert undesirable, tumor-promoting effects by boosting tumor angiogenesis." (PMID 27880939, 2017). "Therefore, we propose PATZ1 as a new prognostic marker of DLBCLs, which may act as a tumor suppressor by enhancing apoptosis through inhibiting and enhancing transcription of BCL6 and BAX, respectively." (PMID 27494852, 2016). "Furthermore, BCOR was found highly expressed in CCSK, suggesting that this gene could represent a key factor in supporting tumor growth, through its interaction with BCL6 and through the altered epigenetic signaling." (PMID 26516930, 2015). "Our data suggest that miR-127 may function as a tumor suppressor that modulates the oncogene BCL6." (PMID 24282530, 2013). "The top ten differentially expressed proteins in patient clusters 1 and 2 showed an upregulation in the tumor periphery and included CD3, CD20, CD8, CD45, PD-1, fibronectin, SMA, CD56, CD4 and BCL6." (PMID 41545625, 2026). "Immunohistochemistry revealed diffuse positivity for CD20, CD10, and BCL6, with C-MYC expression in 40% of tumor cells and a Ki-67 proliferation index of 90%." (PMID 41930191, 2026). "Immunohistochemical stains showed tumor cells positive for CD20, CD10, BCL-6, BCL-2, MUM-1, C-MYC, and with a high Ki-67 index (80%)." (PMID 39897193, 2025). "Most B lymphocytes were derived from the PPLELC tumor and defined into three subsets: plasma (SDC1), follicular B cells (FCER2) and germinal centre (GC) B cells (BCL6)." (PMID 40057671, 2025). "The standard double-color FISH tests confirmed that all tumor cells had translocations involving IGH/BCL2 and IGH/MYC, along with a BCL6 gene rearrangement." (PMID 41142614, 2025). "Taken together, these results suggest that a proper expression of Bcl-6 relative to T-bet in CD4+ T cells at early and late stages of anti-tumor responses was required for the sustained survival outcome of M002 treatment." (PMID 39885128, 2025).